CLDN22 (claudin 22)
Description:
Plays a major role in tight junction-specific obliteration of the intercellular space, through calcium-independent cell-adhesion activity.
Synonyms: CLDN21
Tractability: Antibody: UniProt places it where antibodies can reach, with medium confidence; UniProt predicts a signal peptide or a membrane-spanning region; its Gene Ontology location is reachable by antibodies, with medium confidence.
Gene: Protein-coding gene on chromosome 4 (183,318,100 to 183,320,276, reverse strand). Ensembl gene ENSG00000177300.
Subcellular location: Cell junction, tight junction; Cell membrane
Pathways (Reactome):
Cell-Cell communication: Tight junction interactions
Gene Ontology:
Molecular function: protein binding; identical protein binding; structural molecule activity
Biological process: calcium-independent cell-cell adhesion
Cellular component: bicellular tight junction; plasma membrane; membrane
Genetic constraint (gnomAD): Loss-of-function variants: 0 observed, 0.48 expected, observed/expected ratio (o/e) 0, 90% interval 0 to 1.84. That is too few expected variants to judge how well the gene tolerates losing a copy. Missense variants: 227 observed, 254.52 expected, observed/expected ratio (o/e) 0.89, 90% interval 0.8 to 1. Synonymous variants: 86 observed, 111.27 expected, observed/expected ratio (o/e) 0.77, 90% interval 0.65 to 0.93.
Homologues: Orthologues: chimpanzee CLDN22 (98% identical), macaque CLDN22 (95% identical), dog CLDN24 (73% identical). Paralogues in human: CLDN24 (87% identical), CLDN25 (49% identical), CLDN6 (35% identical), CLDN4 (33% identical), CLDN9 (33% identical), CLDN19 (33% identical), CLDN7 (33% identical), CLDN5 (32% identical), CLDN1 (32% identical), CLDN3 (31% identical), CLDN14 (30% identical), CLDN17 (30% identical), and 10 more.
Diseases named in the same sentence as CLDN22 in open-access papers:
CLDN22 is named in the same sentence as 10 diseases in open-access papers, as found by Europe PMC text mining. Sharing a sentence is not in itself a finding about the gene and the disease. The quoted sentences say what the papers report.
brain astrocytoma (1 paper, 2006). A astrocytoma (excluding glioblastoma) that involves the brain. "Similarly, CLDN22 was only found in 2 breast cancer libraries and one brain astrocytoma library." (PMID 16836752, 2006).
glioma (1 paper, 2025). A benign or malignant brain and spinal cord tumor that arises from glial cells (astrocytes, oligodendrocytes, ependymal cells). "Cluster analysis was performed and CLDN22 was identified as a distinguished biomarker to explore the prognostic value and association with the glioma immune microenvironment." (PMID 41425851, 2025). "Through machine learning approaches, we identified CLDN22 as a biological marker for glioma prognosis." (PMID 41425851, 2025). "Taken together, CLDN22 represents a promising biomarker for glioma prognosis, tumor aggressiveness, and immunotherapy response, warranting further investigation into its molecular mechanisms and clinical applications." (PMID 41425851, 2025). "CLDN22‐positive gliomas likely exhibit a “cold” immune phenotype, characterized by limited immune cell infiltration and an immunosuppressive TME." (PMID 41425851, 2025). "Subsequent GO and KEGG pathway analyses further confirmed CLDN22′s significant role in cell adhesion and tight junction signaling pathways in glioma." (PMID 41425851, 2025). "Our findings reveal the multifaceted role of CLDN22 in glioma biology, prognosis, and immunotherapy response." (PMID 41425851, 2025). "Our comprehensive analysis establishes CLDN22 as a novel prognostic and predictive biomarker in gliomas with significant implications for patient stratification and therapeutic decision‐making." (PMID 41425851, 2025). "K‐M curves demonstrated significantly worse survival outcomes in glioma patients with low CLDN22." (PMID 41425851, 2025). "As a consequence, we identified CLDN22 as a biomarker of glioma prognosis." (PMID 41425851, 2025).
lobular carcinoma (1 paper, 2021). "Moreover, the TCGA dataset revealed reduced mRNA expression of CLDN22 (p = 5.33E-06, fold change =−2.229) in invasive ductal and lobular carcinoma." (PMID 33714203, 2021).
Obesity (1 paper, 2023). Accumulation of substantial excess body fat. "In this study, we focused on the correlation between Ruminococcaceae and Cldn22 to investigate gut microorganisms associated with obesity." (PMID 37019989, 2023). "Our hypothesis regarding the mechanism of involvement of Ruminococcaceae and Cldn22 in obesity is as follows." (PMID 37019989, 2023).
tumor (2 papers, 2015 to 2025). "High CLDN22 expression is significantly associated with poor survival outcomes and more aggressive tumor characteristics." (PMID 41425851, 2025). "High CLDN22 expression correlated with poor prognosis, higher tumor grade, mesenchymal subtype, and IDH wild‐type status." (PMID 41425851, 2025). "Significant genetic losses were assumed to contain potential tumour-suppressor genes: DPYD (1p21.3); CLDN22, CLDN24, ING2, CASP3, SORBS2 (4q34.2-q35.1); DEFB (8p23.1)." (PMID 26019623, 2015).
cancer (1 paper, 2025). A tumor composed of atypical neoplastic, often pleomorphic cells that invade other tissues. "As a nonclassical CLDN family gene, CLDN22 has been relatively understudied in cancer." (PMID 41425851, 2025).
infection (1 paper, 2022). The state of being infected such as from the introduction of a foreign agent such as serum, vaccine, antigenic substance or organism. "Accordingly, the MS‐HRM analyses we used to verify the relationship between methylation proportion and infection status for NR1D1 and CLDN22 serve as a first step toward substantiating the results of the differential methylation analyses in this study." (PMID 36447599, 2022). "We found that methylation level at NR1D1, but not CLDN22, remained related to infection status and that juvenile recruitment probability was positively related to methylation level at NR1D1." (PMID 36447599, 2022). "We found that methylation proportion at NR1D1, but not at CLDN22 remained related to infection status, and that recruitment probability of fledged juveniles infected by S. trachea was positively related to methylation levels at NR1D1." (PMID 36447599, 2022). "We found that methylation proportion at NR1D1, but not at CLDN22, remained related to infection status, which underscores the importance of performing follow‐up studies on candidate genes." (PMID 36447599, 2022). "Then, we used methylation‐sensitive high‐resolution melting to verify that methylation level at NR1D1, but not CLDN22, remained related to infection status in a larger sample dataset, and that juvenile recruitment probability was positively related to methylation level at NR1D1." (PMID 36447599, 2022).
CLDN22 also shares sentences with these, for which no sentence is quoted: asthma (1 paper); breast carcinoma (1); inflammatory bowel disease (1).